CXCL12 (C-X-C motif chemokine ligand 12)
Diseases named in the same sentence as CXCL12 in open-access papers (continued):
Sharing a sentence is not in itself a finding about the gene and the disease.
cancer (continued). "Even in the case of the promoters of the CXCL12, FAP, and SPARC genes, which showed high transcription levels in IVP-9TS as compared to cancer cell lines." (PMID 33804861, 2021). "The results also revealed a decrease in KCNA2, SNCG, and TGFB2 levels with a simultaneous increase in GNB1, CXCL12, SNCA, and OPRK1 expression in G2 cancer compared to control." (PMID 34768458, 2021). "CXCR4 belongs to G protein-coupled receptor superfamily, which selectively binds to stromal cell-derived factor 1 (SDF-1, also called CXCL12) to promote cancer metastasis." (PMID 33897875, 2021). "There was also a decrease in CXCL12, a chemokine ligand expressed by FAP+ CAFs that binds to the CXCR4 receptor on cancer cells, diverting T-cells from malignant cancer cells." (PMID 33499238, 2021). "Some of these potentially metastatic CAF-secreted factors involved in EMT have been studied extensively in the past years in multiple cancer types, such as interleukin-6 (IL-6), osteopontin (OPN), hepatocyte growth factor (HGF), and CXCL12." (PMID 34572947, 2021). "CXCL12 acts as a ligand for CXCR4 and plays a crucial role in autocrine/paracrine signaling in several cancers." (PMID 35053027, 2021). "SDF-1/CXCL12, for which CXCR4 is the cognate receptor for, can be secreted by CAFs in various cancers to promote the growth of stromal fibroblasts." (PMID 34956172, 2021). "Multiple antagonists of CXCR4 including bicyclams (AMD3100) and T22, as well as peptide analogues designed for the N-terminal region of CXCL12, such as TN14003, CTCE-9908, and ALX40-4C are currently used to target CXCR4 in various cancers." (PMID 34298991, 2021). "CXCL12 acts as a ligand for chemokine receptor CXCR4 and CXCR712,14,29, and these signaling axes have shown to be hyper activated in cancer with poor clinical outcome." (PMID 33966046, 2021). "This increases the secretion of two enhancers of cancer cell migration: EGF and stromal cell-derived factor 1 (SDF-1/CXCL12)." (PMID 34207247, 2021). "Numerous studies have shown that both CXCL12 and its receptor CXCR4 are up-regulated in various cancers." (PMID 33962657, 2021). "Reduction of CTNND1 promotes bone metastasis of TNBC cells by facilitating homing cancer cells to bone and the survival of the metastatic cells via upregulating CXCR4/CXCL12 axis and neutrophils Infiltration in bone." (PMID 34830862, 2021). "CXCL12 PEGylated mirror-image l-oligonucleotide (olaptesed-pegol) and CXCR7 inhibitor (CCX733) represent important inhibitors in clinical use for cancer therapies." (PMID 34298991, 2021). "Interaction between CXCL12 and CXCR4 also facilitates the adhesion of cancer cells to microvascular endothelial cells via an integrin β1-based mechanism, which eventually results in an elevated rate of melanoma pulmonary metastases." (PMID 33430277, 2021). "CXCL12 is the main ligand of chemokine receptor 4 (CXCR4) and overexpressed in metastasis of various cancers including CRC." (PMID 34288395, 2021). "It has been demonstrated that CXCL12 and its receptor CXCR4 are involved in cancer cell proliferation, migration, invasion, and angiogenesis." (PMID 33927188, 2021). "In the sections below, we describe how the canonical functions of CXCL12 are misappropriated in PDAC to mediate pro-oncogenic activities, including cancer cell survival and spread, immune suppression, and chemoresistance." (PMID 35008248, 2021). "In the PDX model, most downregulated genes affected by OC-X treatments included MMP9, CXCL12, MMP13, and POSTN within the selected cancer stages." (PMID 34069906, 2021). "AMD3100 inhibits CXCR4 activity and blocks the CXCL12/CXCR4 axis, thereby inhibiting the contribution of both stromal and cancer cells to liver metastasis." (PMID 34555268, 2021). "A previous study showed that CXCL12 secreted by CAFs limits T cell recruitment into the cancer tissue, and CAF depletion or CXCL12 inhibition leads to T cell accumulation, thereby enhancing the therapeutic effect of ICI in a mouse PDAC model." (PMID 34681633, 2021).
cancer (continued). "Chemokine CXCL12 has angiogenic properties and greatly contributes to the outgrowth and metastasis of CXCR4-expressiong cancers." (PMID 33962657, 2021). "Interaction between CXCL12/CXCR4 initiates the phosphorylation of CXCR4, which supports the calcium flux and activation of PI3K, MAPK signalling and thus induce cancer cell proliferation." (PMID 34975909, 2021). "CXCL12 and its receptor, CXCR4, are among the most studied chemokine/chemokine receptors in the scenario of cancer metastasis." (PMID 33390169, 2021). "In this cancer, hypoxia increases the expression of angiogenic factors such as VEGF, CXCL8 and CXCL12." (PMID 33467722, 2021). "BCAF secreted chemokine, CXCL12, binds to the CXCR4 chemokine receptor in cancer cells and regulates signaling pathways that allow growth, chemotherapy resistance, and metastasis." (PMID 34944738, 2021). "SDF-1/CXCL12 is a chemokine used by metastatic cells and cancer stem cells to disseminate and colonize a new niche." (PMID 33672717, 2021). "DPPIV plays a significant role in cancer biology and inhibition of DPPIV promotes cancer metastasis via induction of the CXCL12/CXCR4/mTOR/EMT axis, implying a dissemination-suppressive role in cancer." (PMID 34228231, 2021). "In cancer, CD26 most likely has the most profound effect on the functional properties of CXCL12 and IFN-inducible CXCR3 ligands, who are converted into receptor antagonists upon truncation." (PMID 34503058, 2021). "Normally, this interaction of CXCR4 with CXCL12 regulates stem cell trafficking, but hyperactivation of this axis commonly induces EMT in cancers." (PMID 34572947, 2021). "In prostate cancer, pyruvate kinase M2 (PKM2) released by primary cancer-derived exosomes initiates the downstream release of hypoxia inducible factor-1α (HIF-1α) and CXCL12, which promotes metastatic seeding and outgrowth." (PMID 34745140, 2021). "CXCR4 is the receptor for CXCL12, and an inhibitor of CXCR4, AMD3100, induces T-cell accumulation and works with PD-L1 blockade to reduce cancer cells in KPC mice." (PMID 34336821, 2021). "Subsequently, seven common genes, including FOSL1, S100A9, CXCL12, ID2, PRS6KA3, AREG, and DUSP6, have been used as the target biomarkers for cancer diagnosis and therapy." (PMID 34490085, 2021). "This suggests that both CXCL12 secretion by CAF-S1 and CXCR4 expression in cancer cells are involved in CAF-S1-mediated EMT initiation in BC cells." (PMID 31964880, 2020). "At present, different cancer types have been shown to overexpress C-X-C chemokine receptor type 4 (CXCR4) and to respond to its ligand C-X-C motif chemokine 12 (CXCL12)." (PMID 32260318, 2020). "The blockade of the CXCL12/CXCR4 passage has, therefore, emerged as a potential way of targeted cancer therapy." (PMID 32316469, 2020). "α-SMA+ CAFs at the primary site of triple-negative (TN) breast tumors abundantly produced CXCL12 and IGF-1, the molecules that can select for cancer cells with high Src activity." (PMID 33050237, 2020). "Cancer cells-derived TGF-β upregulates CXCR4 in motile TAMs and guides them towards CXCL12 released by perivascular fibroblasts." (PMID 33096815, 2020). "CAFs secrete a myriad of proteins such as SDF1 (CXCL12), TGF-β, IGF, and CTGF, which have been shown to induce EMT, increasing the motility of cancer cells to promote metastasis." (PMID 33072555, 2020). "CXCL12 binds to CXCR4 and CXCR7 to promote cancer progression and promotes chemoresistance invasion and migration by activating a number of intracellular signaling molecules, including Akt, EGFR, mTOR, NF-κB, and Src." (PMID 32963527, 2020). "Among them, the role of CXCL12/CXCR4 signaling in cancer and metastasis is well known, and CXCR4 has been often targeted with small molecule-antagonists or short CXCL12-derived peptides to limit the pathological processes of cell migration and invasion." (PMID 33233846, 2020).
cancer (continued). "For example, cancer cells metastasize to other organs by upregulating the AA-induced surface chemokine CXCR4; thus, CXCR4 on the CTC surface binds to its ligand CXCL12/SDF-1, which is expressed in the early PMN117." (PMID 33203856, 2020). "SDF-1α, also named chemokine (C-X-C motif) ligand 12 (CXCL12), is the single natural ligand of C-X-C chemokine receptor type (CXCR) 4 and CXCR7, plays an important roles in cancer cell proliferation, migration, and invasion." (PMID 33362712, 2020). "These advances have led to the recognition of CXCL12 and CXCR4 receptors as promising targets for cancer immunotherapy." (PMID 32260318, 2020). "In the case of tumor metastasis, CXCL12 is released from stromal cells within the metastatic microenvironment, which in turn activates CXCR4 on cancer cells to increase cancer cell adhesion, motility and invasion in colon cancer cells." (PMID 32110952, 2020). "In vivo studies demonstrated that activation of CXCL12/CXCR4 accelerates the recruitment of fibroblasts and facilitates cancer stromal formation." (PMID 33363463, 2020). "Cancer cells secrete factors such as NGF, ARTN, CXCL12/SDF-1 which attract Schwann cells, and Schwann cells secrete GDNF, TGF-β and provide NCAM-1-mediated cell-cell interaction to promote cancer cell migration and aggressiveness." (PMID 33050151, 2020). "One of CSC markers which involved in hematopoietic stem cell (HSC) mobilization and homing and other cancers metastasis is the chemokine SDF1/CXCL12 and its receptor CXCR4." (PMID 31983166, 2020). "The CXCL12/CXCR4 axis influences cancer biology, promoting survival, proliferation, and angiogenesis, and plays a pivotal role in directing migration of cancer cells to sites of metastases, making it a prognostic marker and a therapeutic target." (PMID 32260318, 2020). "Over the past few years, a number of inhibitors of CXCL12/CXCR4 have been identified and currently are in different development stages as potential agents for the treatment of cancers." (PMID 32232002, 2020). "While reciprocal crosstalk between cancer cells and CAF-S1 promoted EMT and cell migration via CXCL12 and TGFβ, the CAF-S4 upregulated NOTCH pathway becoming more contractile, and so, facilitating cancer cell invasion." (PMID 32957515, 2020). "The activity of CXCL12, the agonist of CXCR4, has been widely studied and the chemokine is shown to be essential in physiology, development, inflammation, and in cancer metastatic spreading to bone, lungs and brain." (PMID 33072091, 2020). "On the one hand, CAF-S1 induce cancer cell migration and EMT initiation in a CXCL12/TGFβ-dependent manner." (PMID 31964880, 2020). "The interaction between CXCL12 and CXCR4 activates heterotrimeric G proteins, which regulates actin polymerization and cancer cell migration." (PMID 32292657, 2020). "Consistent with this, in recent years genomic findings have provided important insights into the relevance of the CXCL12/CXCR4 axis for pathogenesis, prognostication, and treatment outcome of cancer." (PMID 32784523, 2020). "The activated CAFs release the CXCL12 chemokine, which binds to its two receptors, CXCR4 and ACKR3, highly expressed on the cancer cells surface." (PMID 31275385, 2019). "These cancer cells nested in bone ECM have been found to overexpress chemokine receptors, such as CXCR-4, whose ligand CXCL-12, or SDF-1, is secreted by BMSC." (PMID 31591367, 2019). "SDF-1 (CXCL12), or stromal cell derived factor, is known to allow for TAM movement, and can be secreted directly from cancer cells." (PMID 31263976, 2019). "SIK3 expression also increases the expression of chemokine CXCL12 and its specific receptor CXCR4 on cancer cells, promoting metastasis." (PMID 31888295, 2019). "It has been also observed that CAFs constitute a major stromal compartment actively communicate with cancer cells through growth factors or inflammatory cytokines such as HGF, IL-6, TGF-β, VEGF, FGF, and CXCL12 that can promote tumorigenesis and progression." (PMID 31024835, 2019).
cancer (continued). "In prostate cancer, CXCL12/CXCR4 signaling induces the expression of CD164 and promotes homing of cancer cells to the bone marrow." (PMID 31007847, 2019). "LECs have been shown to release CCL21 and CXCL12 (SDF-1) to recruit CCR7- and CXCR4-expressing cancer cells into sentinel lymph nodes (LNs)." (PMID 31390756, 2019). "Several triple-evidenced genes (MMP9, MMP11, CXCL12, MYL9) appear in three out of the five significantly enriched pathways and in more than half of the 13 cancers." (PMID 30729033, 2019). "Fundamentally, many other CAF-derived factors, such as matrix metallopeptidase 2 (MMP2), CXCL12, TGF-β, and IL-6, can promote the proliferation and invasion of cancer cells in various tumors." (PMID 31462327, 2019). "These cancer initiating cells also express CXCR4 and produce its ligand CXCL12, which leads to recruitment of regulatory DCs." (PMID 31921140, 2019). "CXCL12, also known as stromal cell-derived factor 1 (SDF1), is an important regulator in cancer initiation, angiogenesis, and metastasis." (PMID 31106200, 2019). "CXCL12, or stromal cell-derived factor 1 (SDF1), is, like many other of the CXC chemokines, ubiquitously expressed in many tissues and cell types and its signaling was observed in several cancers, including PDAC." (PMID 31561620, 2019). "The CXCL12/CXCR4 system is overexpressed in a large variety of tumors, and this axis has been increasingly identified as an important target in cancer growth, metastasis, relapse, and resistance to therapy." (PMID 31304688, 2019). "The role of CXCL12/CXCR4 on chemotaxis has been reported in various tumors, as shown by the high levels of CXCL12 in bone, lymph nodes and lung which can attract CXCR4-expressing cancer cells 42-45." (PMID 31534521, 2019). "CXCR4 belongs to G protein-coupled receptor superfamily, which selectively binds to Stromal cell-derived factor 1 (SDF-1), also known as CXCL12 to promote cancer metastasis." (PMID 30678736, 2019). "The role of CXCL12/CXCR4 on chemotaxis in various cancers is vital to the development of metastases, as evidenced by CXCR4-expressing cancer cells migrating via chemotaxis through a CXCL12 gradient to form metastatic lesions 33-35." (PMID 31534521, 2019). "Targeting chemokine interactions and subsequent recruitment of macrophages within tumors, including the CCL2/CCR2 or CXCL12/CXCR4/7 chemokine-chemokine receptor axes, have shown great potential for cancer therapies in various mouse models of cancer metastasis." (PMID 30832375, 2019). "Nonetheless, both CXCL12 and HMGB1 are key players in the TME, where they orchestrate a variety of functions that sustain cancer progression." (PMID 30319638, 2018). "For example, CXCL12/CXCR4 axis promoted stem-like properties, metastatic potential, and radiation resistance in cancer cells." (PMID 30723697, 2018). "PGE2 controls the local recruitment of MDSCs by regulating their expression of CXCL12 and CXCR4 and stimulates tumoral secretion of the pro-angiogenic CXCL1, thus promoting micro-vessel formation and cancer progression." (PMID 30591657, 2018). "The chemokine CXCL12 and its receptors, CXCR4 and CXCR7, participate in tumorigenesis and metastasis in several types of cancers." (PMID 30591657, 2018). "This, together with metastatic predilection sites in CXCL12 high-level organs, suggests the CXCL12-CXCR4 chemokine – receptor interaction as a potential therapeutic target in this cancer." (PMID 29776413, 2018). "Mechanistically, this effect was associated with interactions between a pleiotropic chemokine, CXCL12/SDF1, released by the stem cells and its specific receptor, CXCR4, expressed on the surface of the cancer cells." (PMID 28956065, 2018). "CXCL12 signals through CXCR4 and CXCR7 receptors upregulated on cancer cells, and activates multiple molecular pathways such as the mitogen-activated protein kinase (MAPK), inositol 1,4,5-triphosphate (IP3), and phosphoinositide 3-kinase (PI3K)." (PMID 29416611, 2018).
cancer (continued). "CXCR4 is the first identified receptor for CXCL12, and it is generally recognized that the CXCL12/CXCR4 axis participates in many aspects of cancer, such as the angiogenesis, metastasis, and the survival of cancer cells." (PMID 30574021, 2018). "In addition, Treg with a memory phenotype are frequently recruited through CXCR4/CXCL12 signaling to the bone marrow, a common target of metastasis in humans, further supporting the idea that this cell subset provides an anti-inflammatory environment that sustains cancer progression." (PMID 30319638, 2018). "Accordingly, by secreting CXCL12 and IGF-1, mesenchymal stromal cells from triple negative breast tumors have recently been shown to positively select cancer clones with high Src activity and propensity for bone metastasis." (PMID 29503225, 2018). "CXCL12/CXCR4 axis has been shown to play a significant role in prostate cancer and promoted cancer metastasis." (PMID 30723697, 2018). "CXCL12 is the only ligand for CXCR4 and acts as autocrine/paracrine growth factor for several cancers." (PMID 30564115, 2018). "The second therapeutic aptamer to launch clinical trials for cancer is NOX-A12 (Olaptesed Pegol, NOXXON), an antagonist of the chemokine CXCL12 (or SDF1)." (PMID 29562664, 2018). "Chemokine receptor CXCR4 and its ligand CXCL12 (SDF‐1) have shown to be overexpressed in more than 20 solid tumors and CXCR4 serves as a Cancer Stem Cell (CSC) marker in multiple cancers." (PMID 29460395, 2018). "For example, the presence of a stromal-derived growth factor (SDF-1—CXCL12) and its receptor CXCR4 on bone marrow endothelial cells has been shown to be favourable to cancer cell extravasation from the circulation and their retention in bone marrow." (PMID 29300334, 2018). "Activation of CXCL12/CXCR4 not only is involved in the migration of monocyte but also the migration of T cell 30, dendritic cell 31, neuronal cell as well as cancer cell." (PMID 29105376, 2018). "The CXCL12, also termed SDF-1, is a member of the CXC family of chemokines that regulates leukocyte trafficking and is variably expressed in a number of normal and cancer tissues." (PMID 28176874, 2017). "CXCR4 and its ligand CXCL12 were present in PanIN lesions and PDAC tissues and demonstrated to result in tumor proliferation, cancer progression, angiogenesis, and metastasis." (PMID 29379802, 2017). "CXCL12, CCL22 and CCL17 have been described as critical factors for T-reg attraction in different cancer types." (PMID 28987144, 2017). "A simultaneous and enhanced expression of CXCL12 and CXCR4 has been found in many cancers, such as breast, gastric, pancreatic, ovarian, cervical and oral squamous cell carcinoma." (PMID 29112161, 2017). "First, the upregulation of CXCL12/CXCR4 axis and activation of downstream pathways and their biological functions in proliferation, invasion, and migration of cancer cells are similar." (PMID 28544785, 2017). "We uncovered a novel positive feedback circuit of CXCL12/CXCR4 axis and miR-125b in cancer invasion." (PMID 28176874, 2017). "TAMS can be recruited into the primary tumor by cancer cell derived chemokines and cytokines (e.g. CSF1, VEGFA, CXCL2, CXCL12)." (PMID 29037250, 2017). "Although previous studies have shown CXCL12 to be a marker for many cancers including PTC, we propose that the essential role of CXCL12 methylation is in regulating gene expression in PTC." (PMID 28272462, 2017). "AMPK signaling exerts regulatory effects on cancer cell adhesion, migration and invasion, which is involved in different mechanisms including disruption of the mTOR, TGF-b, Pdlim5, CXCL12, NF-κB and Akt-MDM2-Foxo3a pathways." (PMID 29245964, 2017). "The data suggest that CXCL12 in the CM of EMSCs can enhance the transformation phenotypes of RL95-2 and HEC-1A cancer cells through the CXCR4 receptor and induce an EMT phenotype." (PMID 29383153, 2017).